TRIM22 (tripartite motif containing 22)
Diseases named in the same sentence as TRIM22 in open-access papers (continued):
Sharing a sentence is not in itself a finding about the gene and the disease.
glioma (11 papers, 2020 to 2025). A benign or malignant brain and spinal cord tumor that arises from glial cells (astrocytes, oligodendrocytes, ependymal cells). "TRIM22 exhibited increased expression in primary human GBM specimens, and high TRIM22 correlated with factors associated with higher grade gliomas." (PMID 32814880, 2021). "Furthermore, SP140 and TRIM22 coexpressed in glioma cells with high level of vascular proliferation, TRIM22 is closely associated with the immune cell infiltration." (PMID 38468469, 2024). "Therefore, it is necessary to take into account the association between these molecular features and TRIM22 in future work to further investigate the function and mechanism of TRIM22 in gliomas." (PMID 37258577, 2023). "Polymorphisms affecting the function of TRIM22; thus, it is necessary to further investigate which region of TRIM22 may be associated with the development of human gliomas." (PMID 37258577, 2023). "Studies in glioma cells have shown that TRIM22 binds to the negative regulator of NF-κB, IκBα, and activates the NF-κB signaling pathway by accelerating degradation through ubiquitination modification." (PMID 39895786, 2025). "Elevated TRIM22 levels correlate with aggressive glioma characteristics and activate NF-κB signaling." (PMID 40338274, 2025). "We conducted an immune infiltration analysis using the TIMER method on glioma samples from TCGA to explore the relationship between immune infiltration and TRIM22." (PMID 38468469, 2024). "The effect of SP140 inhibitor in glioma progress and TRIM22/PI3K/AKT signaling pathway was confirmed in U251/U87 glioma cells." (PMID 38468469, 2024). "In gliomas, TRIM22 is believed to be closely associated with the NF‐KB and MAPK pathways, regulating glioma proliferation and invasion." (PMID 38468469, 2024). "Compared with that in the nuclei of low-grade gliomas, TRIM22 expression was greater in the nuclei of high-grade gliomas." (PMID 37258577, 2023). "Results, also indicated that the TRIM22 expression profile was positively correlated with histological subtypes in patients with glioma and was significantly up-regulated in GBM." (PMID 37367937, 2023). "Although the expression level of TRIM22 in the nucleus and cytoplasm was positively correlated with the grade of glioma, the correlation was stronger for nuclear TRIM22 expression." (PMID 37258577, 2023). "We found that the expression of TRIM22 was positively correlated with glioma grade, while there were multiple differences in the molecular profiles in different grades of glioma." (PMID 37258577, 2023). "In this report, the expression of TRIM22 in gliomas was higher than that in normal tissues in mRNA and protein levels." (PMID 37367937, 2023). "WB of lysates prepared from primary tumors (n = 12; WHO grades II–IV) and NBT samples (n = 3) confirmed the overexpression of TRIM22 in human gliomas." (PMID 32814880, 2021). "We demonstrated that TRIM22 promotes glioma cell proliferation in vitro and tumor formation in vivo, and that these properties are linked to its intrinsic E3 Ub ligase activity." (PMID 32814880, 2021). "To characterize its role in the progression of human gliomas, we evaluated TRIM22 protein levels in a cohort of primary gliomas on a tissue microarray and NBT samples using IHC." (PMID 32814880, 2021). "Current research shows that TRIM22 is highly expressed in glioma and can promote the proliferation of tumor cells, while it plays an anti-cancer role in endometrial cancer." (PMID 34736480, 2021). "Our study therefore revealed a novel regulatory mechanism for IκBα degradation and NF-κB activation, and a critical role for TRIM22 in glioma tumorigenesis." (PMID 32814880, 2021).
glioma (continued). "Overexpression of TRIM22, which promoted glioma cell proliferation in vivo and in vitro, was blocked through deletion of the RING domain or substitution of two conserved cysteine sites by alanine." (PMID 32814880, 2021). "Emerging evidence has shown that TRIM22 plays critical roles in tumorigenesis and cancer development, including chronic myeloid leukemia, nonsmall cell lung cancer, and gliomas." (PMID 33299853, 2020). "In vivo studies within murine glioma models show that GSK761 inhibits glioma progression via TRIM22 downregulation and downregulation of the PI3K/AKT pathway, which suggests that SP140 inhibition may allow for reduced glioma invasiveness." (PMID 41188771, 2025). "SP140 inhibitor can suppress glioma progression via TRIM22/PI3K/AKT signaling pathway." (PMID 41188771, 2025). "Considering the well‐documented positive impact of immune cell therapy on the clinical outcomes of gliomas, these findings suggest that TRIM22 may serve as a promising indicator for assessing the potential efficacy of immunotherapy in glioma treatment." (PMID 38468469, 2024). "Finally, increased expression of TRIM22 correlated with other features of more aggressive gliomas, including wild-type IDH1 (P < 0.001) and wild-type ATRX (P = 0.0054)." (PMID 32814880, 2021). "In glioma, TRIM22 is also found to be upregulated, and its downregulation could inhibit tumor growth, invasion, and the Wnt/β-catenin signaling pathway." (PMID 33299853, 2020). "Furthermore, we investigated the mechanisms by which SP140 influences glioma, revealing that it may regulate glioma proliferation and invasion through the TRIM22‐mediated modulation of the PI3K/AKT signaling pathway." (PMID 38468469, 2024). "SP140 inhibitor could suppress glioma progress via TRIM22/PI3K/AKT signaling pathway." (PMID 38468469, 2024). "In addition, high levels of TRIM22 were linked to IDH1-wild type and ATRX-wild type gliomas." (PMID 36139694, 2022). "Thus, we first tested whether TRIM22 induced NF-κB activity in the presence of srIκBα in glioma cells, using the NF-κB luciferase reporter construct." (PMID 32814880, 2021). "Finally, TRIM22 was increased in a cohort of primary GBM samples on a tissue microarray, and high expression of TRIM22 correlated with other clinical parameters associated with progressive gliomas, such as wild-type IDH1 status." (PMID 32814880, 2021). "Therefore, further study is necessary to determine which region of TRIM22 might be relevant to the development of human gliomas." (PMID 32814880, 2021). "Thus, TRIM22 might promote the development of human glioma by facilitating proteasomal-mediated degradation of IκBα, a negative regulator of NF-κB signaling." (PMID 32814880, 2021). "High TRIM22 expression indicates poor survival outcomes and correlates with various WHO glioma grades and immune cell types." (PMID 40338274, 2025). "To further investigate the mechanism by which SP140 regulates glioma progression, we conducted a screening of SP140‐related genes and identified TRIM22 as having a high pathway correlation via Friends analysis." (PMID 38468469, 2024). "TRIM22 was preferentially expressed in high grade gliomas (n = 82; HGG, WHO grade III-IV) compared with low grade gliomas (n = 30; LGG, WHO grade II; P < 0.001)." (PMID 32814880, 2021). "Our research findings indicated that in gliomas, SP140 inhibitors could suppress the PI3K/AKT signaling pathway by downregulating TRIM22, thus inhibiting glioma proliferation and invasion." (PMID 38468469, 2024).
autoimmune disease (7 papers, 2012 to 2024). A disorder resulting from loss of function or tissue destruction of an organ or multiple organs, arising from humoral or cellular immune responses of the individual to their own tissue constituents. "The antiviral TRIM22 protein has been shown to inhibit the replication of a number of viruses, including HIV-1, hepatitis B, and influenza A. TRIM22 expression has also been associated with multiple sclerosis, cancer, and autoimmune disease." (PMID 24983760, 2014). "In addition, TRIM22 has also been implicated in cellular differentiation and proliferation and may play a role in certain cancers and autoimmune diseases." (PMID 22649727, 2012). "TRIM22 is an interferon-induced protein that potently inhibits the replication of diverse viruses such as HIV-1, HCV and HBV; and the overexpression of TRIM22 activates NF-κB in a dose-dependent manner, promoting autoimmune diseases." (PMID 27590274, 2016). "Although it is also unclear what role TRIM22 plays in this disease, it is notable that several other TRIM proteins, including TRIM 21, 25, 56, and 68, have been linked to SLE and other autoimmune diseases." (PMID 22649727, 2012). "TRIM22 is a viral restriction factor that may play a role in certain autoimmune diseases such as multiple sclerosis." (PMID 35495164, 2022). "In conclusion, we have presented genetic data supporting a role of the retroviral restriction genes, TRIM5, TRIM22 and BST2 in the autoimmune disease multiple sclerosis." (PMID 24066097, 2013).
glioblastoma (7 papers, 2021 to 2025). The most malignant astrocytic tumor (WHO grade IV). "For instance, TRIM22 can activate the NF-κB signaling pathway by degrading IκBα, promoting glioblastoma cell proliferation." (PMID 39988672, 2025). "This elevated expression of TRIM22 in ESCC is consistent with findings in glioblastoma, suggesting a potential role for TRIM22 in the pathogenesis of both cancers." (PMID 40075566, 2025). "Key aspects of the role of the multi-functional protein TRIM22 in promoting the proliferation of glioblastoma, the most common malignant brain tumor in adults, have been identified in human glioblastoma cells and laboratory mice." (PMID 37258577, 2023). "Inhibiting TRIM22 with a candidate drug suggested that targeting it or the processes it affects could yield new treatments for glioblastoma." (PMID 37258577, 2023). "TRIM22 is highly expressed in several tumors, including glioblastoma and colon cancer." (PMID 37367937, 2023). "TRIM22 is upregulated in glioblastoma (GBM) and promotes tumor growth and progression by modulating the stability of IKKγ and IkBα." (PMID 38199981, 2024).
lung carcinoma (7 papers, 2017 to 2024). "TRIM22 promotes the invading ability of lung cancer cells via the downregulation of E-cadherin and upregulation of N-cadherin." (PMID 33879231, 2021). "As for lung cancer tissues, 55.6% (70/126) cases showed high TRIM22 expression while the rest showed weak/negative staining." (PMID 28977927, 2017). "To further explore the potential mechanism of TRIM22 in the regulation of lung cancer invasion, we checked epithelial-mesenchymal transition (EMT) related proteins." (PMID 28977927, 2017). "In this study, we demonstrated that TRIM22 promoted invading ability of lung cancer cells using matrigel invasion assay." (PMID 28977927, 2017). "In conclusion, this study delineates the clinical significance and biological function of TRIM22 in lung cancer progression." (PMID 28977927, 2017). "For the first time, we showed that TRIM22 protein expression was significantly upregulated in 55.6% lung cancer specimens examined, which significantly correlated with positive lymph node metastasis and advanced TNM stage." (PMID 28977927, 2017). "Based on the literature data, TRIM22 could manifest oncogenic properties in leukemia or lung cancer." (PMID 36552887, 2022). "Recent studies have reported that TRIM22 plays a role in lung cancer and leukemia, which indicates that TRIM22 may be involved in the regulation of malignant tumors." (PMID 34489426, 2021). "However, it should be noted that previous studies have identified TRIM22 as an oncogene in lung cancer and leukemia, which suggests that the transcriptional regulation mechanism of TRIM22 is rather complex." (PMID 34489426, 2021). "Relative expression level of TRIM22 was analyzed in a panel of lung cancer cell lines." (PMID 28977927, 2017). "Our results showed that TRIM22 could induce Snail expression in lung cancer cells, suggesting TRIM22 control EMT process through induction of Snail." (PMID 28977927, 2017). "In contrast, TRIM22 siRNA reversed this process, suggesting that TRIM22 could be a novel promoter of EMT process in lung cancer cells." (PMID 28977927, 2017). "TRIM22 also positively regulated cell migration rate in lung cancer cells." (PMID 28977927, 2017). "Western blot analysis showed significant TRIM22 protein overexpression in lung cancer tissues." (PMID 28977927, 2017). "Importantly, we showed that TRIM22 overexpression correlated poor survival of lung cancer patients." (PMID 28977927, 2017).
COVID-19 (6 papers, 2021 to 2025). A disease caused by infection with severe acute respiratory syndrome coronavirus 2. "The present study aimed to assess of the relationship between TRIM22 single-nucleotide polymorphisms and clinical parameters with the coronavirus disease 2019 (COVID-19) infection severity." (PMID 36028902, 2022). "A reduced abundance of naïve CD8 T cells with decreased expression of antiviral defense genes (i.e., IFITM3 and TRIM22) was identified in aged patients with severe COVID-19." (PMID 37199576, 2023). "Due to TRIM22 constitutive expression in epithelial cells, its potential role in limiting the SARS-CoV-2 infection causing the currently towering COVID-19 pandemic is remarkable." (PMID 36028902, 2022). "Further, it was suggested that upregulation of TRIM22 in COVID-19 patients might contribute to controlling the SARS-CoV-2 infection, resulting in a milder infection with fewer severe symptoms." (PMID 38932287, 2024). "In brief, the severity of COVID-19 infection was significantly higher in patients with TRIM22 rs1063303 GG, TRIM22 rs7935564 GG, and TRIM22 rs7113258 TT genotypes, whereas other TRIM22 genotypes (rs1063303 CC, rs7935564 AA, and rs7113258 AA genotypes) were observed in COVID-19 improved patients." (PMID 36028902, 2022).
endometrial cancer (6 papers, 2021 to 2024). Primary or metastatic malignant neoplasm involving the endometrium (mucous membrane that lines the endometrial cavity). "For instance, overexpression of TRIM22 has been shown to decrease the proliferation and migration of endometrial cancer cells as knockdown of TRIM22 was found to accelerate cancer progression via NOD‐NF‐κB pathway." (PMID 36881608, 2023). "In endometrial cancer, TRIM22 is proven to inhibit tumor growth by NF-κB signaling pathway, and conferred a favorable prognosis." (PMID 33763372, 2021). "The expression of TRIM22 is reduced in tumor tissues, and the overexpression of TRIM22 could inhibit the migration, invasion, proliferation, and cell cycle activity in endometrial cancer." (PMID 38380081, 2024).
gastric cancer (6 papers, 2021 to 2025). A primary or metastatic malignant neoplasm involving the stomach. "TRIM22 directly interacts with Smad2 to suppress gastric cancer cell proliferation, and Smad2 overexpression counteracts TRIM22-mediated inhibition of cell proliferation and migration." (PMID 40936722, 2025). "In gastric cancer cells, TRIM22 inhibits cancer cell proliferation and migration by reducing the phosphorylation of SMAD2." (PMID 38199981, 2024). "TRIM22 protein expression was downregulated in gastric cancer tissue compared to the adjacent group, and the H-score was 103.6 ± 30.5 vs 142.6 ± 28.8, with a significant difference (P < 0.01)." (PMID 34489426, 2021). "We also found that the expression of TRIM22 protein and mRNA decreased in gastric cancer cell lines compared with that in the immortalized normal gastric epithelial cell line GES-1 (P < 0.01)." (PMID 34489426, 2021). "In this study, we measured the expression of TRIM22 in gastric cancer tissues and cells and investigated its effect on cell proliferation using a lentiviral-mediated overexpression approach." (PMID 34489426, 2021). "The expression of TRIM22 protein in 90 pairs of gastric cancer and adjacent tissues was measured by immunohistochemistry." (PMID 34489426, 2021). "Overexpression of TRIM22 significantly inhibited the proliferation, colony formation, and migration of gastric cancer cells and downregulated the expression of HSPA6." (PMID 34489426, 2021). "To further identify the downstream genes of TRIM22 in gastric cancer, we analyzed the differentially expressed genes between TRIM22-overexpressing and control cells using RNA-Seq." (PMID 34489426, 2021). "We found that TRIM22 mRNA and protein expression was abnormally low in gastric cancer tissues and cells and correlated with tumor size and depth of invasion." (PMID 34489426, 2021). "TRIM22 had a low expression level in gastric cancer tissues and cells." (PMID 39768197, 2024). "Moreover, the anti-growth effect of TRIM22, which was observed in subcutaneous xenograft experiments, can be reversed by the upregulation of Smad2, indicating that TRIM22 suppressed gastric cancer progression by blocking the TGF-β/Smad pathway." (PMID 39768197, 2024). "TRIM22 mRNA expression was also significantly downregulated in gastric cancer tissues (P < 0.05)." (PMID 34489426, 2021). "Furthermore, we divided gastric cancer tissues into a TRIM22-positive group (n = 27) and a TRIM22-negative group (n = 63)." (PMID 34489426, 2021). "In this study, we investigated the expression and biological role of TRIM22 in gastric cancer." (PMID 34489426, 2021). "Our study indicates that TRIM22 has an important role in the development of gastric cancer and may inhibit the proliferation of gastric cancer cells through Smad2." (PMID 34489426, 2021). "Because TRIM22 could inhibit Smad2 phosphorylation, we speculated that TRIM22 might regulate the proliferation and migration of gastric cancer cells through Smad2." (PMID 34489426, 2021). "The results of qPCR and immunohistochemistry showed that the expression of TRIM22 mRNA and protein was abnormally decreased in gastric cancer, as well as in gastric cancer cells, which indicated that there was an abnormal transcription of the TRIM22 gene in gastric cancer." (PMID 34489426, 2021). "In conclusion, our results showed that TRIM22 expression was abnormally downregulated in gastric cancer and that TRIM22 could inhibit the proliferation and migration of gastric cancer cells by affecting Smad2 protein phosphorylation." (PMID 34489426, 2021). "Therefore, this study aimed to explore whether TRIM22 is involved in the regulation of the occurrence and development of gastric cancer." (PMID 34489426, 2021). "However, the role of TRIM22 in gastric cancer remains unclear." (PMID 34489426, 2021).
gastric cancer (continued). "Further cellular functional assays showed that TRIM22 overexpression significantly inhibited the proliferation and migration of gastric cancer cells, which suggested that TRIM22 may be a tumor suppressor gene and participate in the regulation of the occurrence and development of gastric cancer." (PMID 34489426, 2021). "For instance, in GBM, TRIM22 plays an important role in promoting GBM proliferation and chemoresistance to temozolomide, while in cancers like hepatocellular carcinoma (HCC), gastric cancer (GC), and BC42,66,67, TRIM22 functions as a tumor suppressor." (PMID 40593126, 2025). "In gastric cancer, ubiquitin-related enzymes such as TRIM22 and USP32 promote the proliferation and invasion of gastric cancer cells by affecting the stability of the SMAD2 protein, which is highly expressed in gastric cancer." (PMID 37685308, 2023). "In addition, Kaplan–Meier survival analysis showed that patients who had TRIM22-positive gastric cancer had a better prognosis than those with TRIM22-negative cancer with a median survival of 50.0 months vs. 29.0 months." (PMID 34489426, 2021).
multiple sclerosis (6 papers, 2013 to 2022). A progressive autoimmune disorder affecting the central nervous system resulting in demyelination. "However, the role of TRIM22 in the development of multiple sclerosis (MS) has been debatable." (PMID 35609018, 2022). "Strikingly, polymorphisms in TRIM5, TRIM22, and BST2, but not APOBECs or TREX1 were significantly associated to another neuroinflammatory disorder, multiple sclerosis." (PMID 29872426, 2018).